MTAP (methylthioadenosine phosphorylase)
Diseases named in the same sentence as MTAP in open-access papers (continued):
Sharing a sentence is not in itself a finding about the gene and the disease.
cancer (continued). "Genetic knockdown screening libraries revealed that in the 15% of cancers with MTAP loss, enhanced dependence is conferred on methylthioadenosine transferase 2 alpha (MAT2a, EC:2.5.1.6) and protein arginine methyltransferase 5 (PRMT5, EC:2.1.1.320)." (PMID 38000655, 2024). "Next-generation PRMT5 inhibitors such as MRTX1719, TNG908, and TNG462 were subsequently designed to fully inhibit PRMT5 activity in MTAP-deficient cancer cells while sparing normal cells." (PMID 39337530, 2024). "Therapeutic inhibition of PRMT5 has been proposed as synthetically lethal in cancers with MTAP loss." (PMID 38480701, 2024). "The previous research has studied the effect of MTA in combination with purine analogues such as 2’-fluoroadenine (2FA) in MTAP-deficient cancers." (PMID 38923999, 2024). "Further efforts are necessary to identify alternative means of targeting PRMT5 and MTA2 in MTAP-ve cancers to benefit from the high-MTA environment of MTAP-deficient cancers." (PMID 36913304, 2023). "It is of considerable note that deletions involving methylthioadenosine phosphorylase (MTAP)—a pivotal enzyme in the methionine salvage pathway—have been implicated in multiple cancer phenotypes." (PMID 38034101, 2023). "PRMT5 loss is synthetically lethal with MTAP deficiency, which occurs frequently in many cancer types, including PCa, providing an additional rationale for the use of PRMT5 inhibitors in selected patient populations." (PMID 38201511, 2023). "Homozygous deletion of methylthioadenosine phosphorylase (MTAP) frequently occurs in cancer because of its proximity to the CDKN2A gene, which encodes p16/INK4A and p19/ARF." (PMID 36980950, 2023). "Therapeutic inhibition of PRMT5 has been proposed as synthetically lethal in cancers with loss of MTAP." (PMID 37502925, 2023). "Many cancers harbor a homozygous deletion of the gene encoding methylthioadenosine phosphorylase (MTAP), a key enzyme in the methionine salvage pathway." (PMID 35163841, 2022). "Based on this functional basis, therapeutic strategies have been developed to target MTAP loss for cancer treatment." (PMID 36572880, 2022). "MTAP frequently becomes deficient in cancer and reprograms the metabolism by building up methylthioadenosine." (PMID 36313281, 2022). "Future efforts will need to be directed at understanding the importance of reduced protein sDMAylation on other proteins that are affected by loss of MTAP and how this plays a role in cancer development." (PMID 35963436, 2022). "In MTAP-deficient cancers, MTA accumulation selectively inhibits protein arginine methyltransferase 5 (PRMT5) enzyme activity and increases PRMT5 inhibition sensitivity." (PMID 35979371, 2022). "Even though MTAP is associated with several cancers, the functional relevance and the biological mechanism are yet to be fully understood." (PMID 36572880, 2022). "A significant positive correlation was observed between gene expression of CD274 (PD-L1) and CDKN2A/MTAP in a subset of TCGA cancers, which indicates decreased PD-L1 expression in cancers with 9p21 loss." (PMID 34556668, 2021). "For example, it has been shown in cancer cell lines that MTAP loss (present in >99% of tumors with CDKN2A loss) results in an accumulation of the metabolite 5′-methylthioadenosine (MTA) in tumor cells and the extracellular environment." (PMID 34556668, 2021). "In fact, Zhao and Zhao in a tumor suppressor pan-cancer study reported the association between copy number loss (9p21) and reduced MTAP mRNA expression." (PMID 32093414, 2020). "This vulnerability can be exploited therapeutically, and PRMT5 targeting in MTAP‐deficient cancers has indeed become the focus of recent research." (PMID 32301278, 2020). "Heterozygous deletion of p16/CDKN2A is prevalent in cancer, and these mutations commonly involve a codeletion of adjacent genes, including methylthioadenosine phosphorylase (MTAP)." (PMID 30922330, 2019).
cancer (continued). "The 9p21.3 region also harbors the cancer-associated gene MTAP, which is adjacent to the CDKN2A-CDKN2B cluster." (PMID 29190909, 2017). "In cancer cells, MTAP deficiency leads to partial metabolite-based inhibition of PRMT5 by altering the ratio of MTA to SAM, which results in a decreased H4R3me2s mark." (PMID 29163371, 2017). "Methylthioadenosine Phosphorylase (MTAP) is a tumor suppressor gene that is frequently deleted in human cancers and encodes an enzyme responsible for the catabolism of the polyamine byproduct 5′deoxy-5′-methylthioadenosine (MTA)." (PMID 25387827, 2014). "Many genes in this region (e.g., the CDKN2A/CDKN2B locus and MTAP) were found to be associated with different types of cancer." (PMID 25522020, 2014). "The 5' gene, MTAP, encodes for a methylthioadenosine phosphorylase that has been frequently observed to be co-deleted with tumor suppressor gene encoding p16 in numerous cancers." (PMID 22032724, 2011). "Other genes implicated in cancer also map to 9p21: MTAP (methylthioadenosine phosphorylase), and interferon (IFN) α and β clusters." (PMID 15305192, 2004). "Furthermore, elucidating the impact of MTAP loss in different cancers will pave the way for novel therapeutic strategies based on specific tumor types, moving beyond a one-size-fits-all approach." (PMID 41439984, 2025). "MTAP deficiency has also been linked to cancer progression in other tumor entities." (PMID 39668577, 2025). "Given the selective vulnerability of MTAP-deficient cancer cells to CB-839 treatment and the immunoregulatory role of CXCL10, we next evaluated whether glutaminase inhibition could enhance CXCL10 expression." (PMID 41246302, 2025). "It appears possible that the observed link between MTAP deficiency and unfavorable tumor phenotype is driven by the markedly lower level of measurable immune response in the tumor microenvironment of MTAP‐deficient cancers." (PMID 39668577, 2025). "Consequently, in cancers with MTAP loss, increased intracellular MTA leads to reduced MAT2A levels and decreased PRMT5 activity." (PMID 40506895, 2025). "Therefore, MAT2A inhibitors have the potential to be used as therapeutic candidates for MTAP deficient cancers." (PMID 40240755, 2025). "However, over the years, it has become widely accepted that MTAP deletion offers a significant potential for targeted therapy in cancers with 9p21.3 loss." (PMID 41439984, 2025). "In most cancer types, MTAP deficiency is caused by homozygous co-deletion with cyclin dependent kinase inhibitor 2A (CDKN2A) gene at 9p21.3 which is homozygously deleted in up to 15 % of all human cancers." (PMID 40554389, 2025). "In this review, we consolidate the existing literature along with our systematic analysis to provide an updated perspective on the incidence of MTAP loss in different cancers and elucidate its impact on metabolism, immune microenvironment, and tumor progression." (PMID 41439984, 2025). "Second-generation inhibitors exploit the metabolic vulnerability of MTAP-deficient cancers." (PMID 41204384, 2025). "MAT2A inhibitors, such as SCR-7952, show strong and selective anti-tumor activity in both in vitro and in vivo models of MTAP-deficient cancer, and can produce synergistic antitumor effects when used competitively or cooperatively with S-AdenosylMethionine and PRMT 5 inhibitors." (PMID 40240755, 2025). "In MTAP-deficient cancer cells, adenine synthesis can only be maintained by de novo biosynthesis." (PMID 40227771, 2025). "MTAP gene and protein loss is common in 10-15% of all cancers and causes a poor prognosis." (PMID 41583489, 2025). "Understanding the adaption of processes to the increased MTA concentration in cancer cells with MTAP deletion may be crucial for understanding the causes of resistance to PRMT5 and MAT2A inhibitor therapies." (PMID 41465382, 2025).
cancer (continued). "Researchers believe that the vulnerability of PRMT5 in MTAP‐deficient cancers may extend both upstream of PRMT5 (methionine adenosyltransferase 2A, MAT2A) and downstream of PRMT5 (RIOK1 and other PRMT5 co‐complex members)." (PMID 39711357, 2024). "Thus, to confirm our data and further evaluate the impact of MTA on intra-tumoral immune cell crosstalk, additional studies in MTAP-deficient tumor mouse models or ex vivo analyses of tumor tissues of different cancer entities are needed." (PMID 39768204, 2024). "Nevertheless, candesartan is useful for managing the side effects of hypertension caused by bevacizumab, and even a modest impact against PRMT5 could be of value in targeting MTAP-deficient cancers." (PMID 38187871, 2024). "The stronger impact on cancer cells may be attributed to the deficiency of 5-methylthioadenosine phosphorylase (MTAP), a key enzyme in the methionine salvage pathway, which is also notably absent in most cancers." (PMID 38923999, 2024). "Since first generation PRMT5i do not target the PRMT5-MTA complex, it is not clear yet whether they will be clinically active in patients with MTAP-deficient cancers." (PMID 37502925, 2023). "In these MTAP-deficient cancer cells, inhibition of PRMT5 inhibits tumor growth." (PMID 37298093, 2023). "Collectively, MTAP loss may be a promising therapeutic target for developing novel strategy of cancer therapy." (PMID 37091983, 2023). "MTAP is abundant in normal cells but is deficient in many cancers." (PMID 37091983, 2023). "In this section, we summarized the role of MTAP loss implicated in different types of cancer." (PMID 37091983, 2023). "Endogenous inhibition of PRMT5 may also render MTAP-deficient cancers more sensitive to type I PRMT inhibition." (PMID 37237172, 2023). "In addition, we have also reviewed the relevance of MTAP in other cancers, specific inhibitors, and the associated clinical trials." (PMID 36572880, 2022). "Thus, identification of viable molecular targets is of utmost importance for developing effective therapeutic options for MTAP‐loss cancer." (PMID 35766227, 2022). "Moreover, the approach that recognizes differentially symmetrically dimethylated proteins by methylproteomic screening seems a promising strategy to identify potential therapeutic targets and to address the unmet needs of combating MTAP‐deficient cancers." (PMID 35766227, 2022). "Inhibition of MTAP expression may be responsible for the development of tumor and MTAP polymorphisms were associated with some cancer risk, including OS." (PMID 35860595, 2022). "Today, we know that loss of MTAP expression is frequent (>10%) in a large number of different human cancers, including glioblastoma, mesothelioma, bladder cancer, pancreatic adenocarcinoma, head and neck cancer, non–small cell lung cancer, melanoma, and diffuse large-cell lymphoma." (PMID 35963436, 2022). "Mutation of MTAP results in dysregulated epigenetics and cancer cell stemness." (PMID 36572880, 2022). "MTA together with 6-thiogunaine (6-TG) provides selective treatment for cancers with MTAP loss." (PMID 36572880, 2022). "The deficiency of MTAP, an enzyme of the adenine salvage pathway, occurs in some cancers." (PMID 35379845, 2022). "Moreover, several studies have looked into the molecular mechanism underlying the tumor suppressor role of MTAP in human cancers." (PMID 35541910, 2022). "As such, MTAP-deficient cancer cells are inherently sensitive to inhibition of PRMT1." (PMID 33691794, 2021). "MTAP-deficient cancers are known to acquire vulnerability to arginine methyltransferase PRMT5 depletion, which may be a novel target of an anticancer drug." (PMID 32887687, 2020). "The MTAP-deficient cancer cells are more sensitive to the PRMT5 inhibitor." (PMID 30283496, 2018). "Consequently, cancers with loss of MTAP and therefore already impaired PRMT5 activity are hypersensitive toward PRMT5 inhibitors." (PMID 28725214, 2017).
cancer (continued). "Loss of MTAP expression has been observed in many cancer cell lines including TNBC." (PMID 27579534, 2016). "However, MTAP deletion is less frequent observed in cancer patients with RB1 mutation." (PMID 41465382, 2025). "Consequently, cancer cells with MTAP deletion are highly susceptible to PRMT5 inhibition." (PMID 39885614, 2025). "While targeting PRMT5 presents a therapeutic strategy for MTAP-deficient tumors, these findings highlight the potential immunosuppressive side effects on T cell responses, underscoring the need for careful evaluation of immune system impacts in cancer therapy development." (PMID 39461979, 2024). "Two recent studies correlated CDKN2A/MTAP loss as an ICT resistance marker in several pan cancers but were limited by the small number of HPV– HNSC patients and could not evaluate the contributions and interactions of other chromosomal sites or genes to this observation." (PMID 36395141, 2022). "Although not yet tested in GEP-NENs, loss of the enzyme methylthioadenosine phosphorylase (MTAP) due to genetic deletion of the nearby CDKN2A tumor suppressor may confer dependence on PRMT5 arginine methyltransferase activity as happens in other cancers." (PMID 35747820, 2022). "Importantly, MTAP loss determines the accumulation of the MTA substrate, a natural inhibitor of protein arginine methyltransferase 5 (PRMT5), thus generating a hypomorphic PRMT5 state in MTAP‐deficient cancers that are, in this way, selectively sensitized to further PRMT5 inhibition." (PMID 32301278, 2020). "Finally, germline mutations in humans that disrupt primate specific MTAP exons are associated with diaphyseal medullary stenosis with malignant fibrous histiocytoma, a rare genetic disease associated with bone dysplasia and cancer." (PMID 25387827, 2014). "TNG462 is a next‐generation second‐generation inhibitor that targets the PRMT5–MTA complex and is primarily intended for MTAP‐deleted cancers." (PMID 41537447, 2026). "Previously, we described a novel strategy to specifically target MTAP -deleted cancer cells by combining the antipurine prodrug 2-fluoroadenine (2FA) with MTA." (PMID 42239469, 2026). "MTAP activity was also measured across a panel of cancer cell lines to determine intracellular MTAP levels and to complement whole-blood measurements." (PMID 41825704, 2026). "In vit ro, this combination efficiently killed MTAP- cancer cells, but in vivo the combination was much less effective in vivo." (PMID 42239469, 2026). "Homozygous deletion of MTAP occurs in approximately 15% of all human cancers due to its chromosomal proximity to the CDKN2A/B locus." (PMID 41825704, 2026). "Approximately 15% of human cancers harbour MTAP deletions, making this axis an attractive focus of drug discovery." (PMID 41537447, 2026). "MTAP-KO cancer cells displayed significantly lower luciferase activity, and deletion mapping localized the responsible regulatory elements to the proximal 1-kb region of the CXCL10 promoter." (PMID 41246302, 2025). "Inhibition of themethyltransferase enzyme PRMT5 by MTAaccumulationis a vulnerability of MTAP-deleted cancers." (PMID 40102181, 2025). "Protein arginine methyltransferase 5 (PRMT5) is a key regulator of gene expression and RNA splicing, with therapeutic potential demonstrated in MTAP-deleted cancers." (PMID 40846633, 2025). "The inhibitor demonstrates selective activity against MTAP-depleted cancers both in vitro and in vivo, effectively reducing sDMA levels in cancer cells while sparing normal tissues, thereby showcasing a favorable therapeutic window." (PMID 40157258, 2025). "Homozygous deletion of the 9p21.3 genomic locus spanning the CDKN2A/B and MTAP genes is an event affecting 15% of cancers." (PMID 41439984, 2025). "The promising effects of PRMT5 inhibitors in targeted therapy of methylthioadenosine phosphorylase-deleted cancers are particularly highlighted." (PMID 39826691, 2025).
cancer (continued). "In this context, MAT2A inhibition has been shown to suppress MTAP‐deleted cancers via a synthetic lethality mechanism that involves further reduced PRMT5 activity." (PMID 40552664, 2025). "Despite pronounced selectivity in MTAP-deleted cancer cells, the molecular mode of action for MTA-cooperative inhibitors cannot be directly measured in a pathophysiological setting." (PMID 41339334, 2025). "Previous large-scale functional screens identified PRMT5 as a synthetic lethal target in MTAP-deleted cancer cells." (PMID 41246302, 2025). "Recent studies have demonstrated that the inhibition of MAT2A results in a selective antiproliferative effect in cancers characterized by MTAP deletion." (PMID 40590219, 2025). "MTAP deletion occurs slightly more frequently in men, and the median age of patients at cancer diagnosis is 65 years." (PMID 41465382, 2025). "Initial screening using MTT assays identified 53 candidate compounds with selective cytotoxicity against MTAP-KO cancer cells." (PMID 41246302, 2025). "MTA-dependent compounds inhibit PRMT5 activity in an MTA-cooperative manner and selectively kill MTAP-deleted cancer cells while sparing MTAP wild-type (WT) cells." (PMID 40377999, 2025). "The methylthioadenosine phosphorylase (MTAP) gene is frequently lost in cancers through codeletion with the CDKN2A tumor suppressor gene." (PMID 40377999, 2025). "Immune checkpoint inhibitors (ICIs) in the treatment of MTAP-null cancers have garnered interest in the research field due to the synergistic effect of PRMT5 inhibition with anti-programmed cell death protein (PD1) drugs." (PMID 41439984, 2025). "Given that gene deletion was the most common alteration observed for MTAP and that its role in cancer is supported by evidence of pathogenicity, we further focused the analysis on MTAP loss cases (N=128)." (PMID 38350716, 2025). "MTAP deletion occurs in approximately 15% of all cancers and is particularly prevalent in certain solid tumors, such as gliomas, non–small cell lung cancer, and pancreatic cancer." (PMID 40590221, 2025). "PRMT5 inhibitors have demonstrated synthetic lethality in cancers with MTAP deletions, selectively inducing cancer cell death." (PMID 40846633, 2025). "MTAP is often codeleted with CDKN2A/B in a variety of cancers through chromosome 9p21.3 microdeletion events." (PMID 38350716, 2025). "Further analysis using the TCGA pan-cancer dataset consolidated the positive correlation between MTAP and CXCL10 expression." (PMID 41246302, 2025). "Following hit optimization, MRTX1719 was characterized as a peptide-substrate-competitive, MTA-cooperative inhibitor with promising selectivity for MTAP-deleted cancer cells." (PMID 41339334, 2025). "The Met salvage pathway, essential for Met replenishment independent of exogenous sources, involves enzymes such as methylthioadenosine phosphorylase (MTAP) and methionine synthase (MS), which are frequently downregulated in cancer cells." (PMID 40535116, 2025). "While CDKN2A is a well-established tumor suppressor gene, the role of MTAP in tumorigenesis varies across cancer types." (PMID 41439984, 2025). "In our study, we found that MTAP alteration prevalence in GI cancers ranges from 5% to 10% across various cancer types." (PMID 38350716, 2025). "In summary, it should be emphasized that the detection of MTAP gene deletion, one of the most frequently observed genetic abnormalities in cancer cells, opens new therapeutic opportunities for cancer patients." (PMID 41465382, 2025). "Either way, the effectiveness of PRMT5 and MAT2A inhibitors depends on the accumulation of MTA in cancer cells with MTAP gene deletion." (PMID 41465382, 2025). "In ERG positive cancers, MTAP expression decreased with advanced pT stage (p < 0.0001), classical (p = 0.0004) and quantitative Gleason grade (p = 0.0005), and low MTAP expression was significantly linked to early PSA recurrence (p = 0.0012)." (PMID 40554389, 2025).